IL27 (interleukin 27)
Diseases named in the same sentence as IL27 in open-access papers (continued):
Sharing a sentence is not in itself a finding about the gene and the disease.
falciparum malaria (2 papers, 2020). "Our findings show that IL-27 is regulated during falciparum malaria in adults, potentially mediating both inflammatory and anti-inflammatory effects." (PMID 31964363, 2020). "Both IP-10 (effects on T cells) and sCD25 (released from T cells upon activation) are related to T cell function/activation and these data further link IL-27 to T cell pathology during falciparum malaria." (PMID 31964363, 2020). "The strong correlation between IL-27 and vWF as a marker of endothelial cell activation also support a link between endothelial cells and IL-27 in vivo during falciparum malaria, either as a cellular source, cellular target or both." (PMID 31964363, 2020). "To elucidate any possible consequences of the increased IL-27 levels in falciparum malaria, we examined the effect of IL-27 on the release of prototypical inflammatory cytokines (i.e., IL-6 and IL-8) in hemozoin-exposed HAoEC." (PMID 31964363, 2020). "Our findings show that IL-27 is regulated during falciparum malaria, mediating both inflammatory and anti-inflammatory effects, potentially playing an immune-regulatory role during falciparum malaria." (PMID 31964363, 2020). "Decreased levels of IL-27 have been found in infants with severe falciparum malaria." (PMID 31964363, 2020). "Finally, to elucidate any potential consequences of altered IL-27 levels during falciparum malaria in vivo, we examined the ability of IL-27 to modulate hemozoin-induced release of various inflammatory cytokines in peripheral blood mononuclear cells (PBMC) and endothelial cells." (PMID 31964363, 2020).
Fever (2 papers, 2022 to 2024). Body temperature elevated above the normal range. "Analogously, this study revealed a significant association between the IL-27 rs17855750 GG genotype and fever." (PMID 38690286, 2024). "The interleukin cytokines IL6, IL27, and IL17B, were upregulated in the medium and high dose groups resulting in hemorrhagic fever by cytokine storm." (PMID 35854219, 2022).
Graves disease (2 papers, 2021). Graves' disease is an autoimmune disorder that leads to overactivity of the thyroid gland (hyperthyroidism).It is caused by an abnormal immune system response that causes the thyroid gland to produce too much thyroid hormones. "In contrast, a recent study found reduced IL-27 serum levels in patients with Graves’ disease, suggesting a possible anti-inflammatory role of these cytokines." (PMID 34439776, 2021). "A possible explanation for these differences is the effect of IL-27 on the Th1 to Th2 ratio, which is dominant in HD, whereas it is non-dominant in Graves’ disease." (PMID 34439776, 2021).
hematoma (2 papers, 2019 to 2022). A hematoma is a collection of blood from a vascular structure into an extravascular space. "IL-27 and lactoferrin reduced edema, enhanced hematoma clearance, and improved neurological outcomes in experimental ICH." (PMID 30836997, 2019). "Researchers observed that IL-27 was upregulated centrally and peripherally after ICH, and IL-27 treatment improved ICH outcomes by reducing edema and increasing iron and hematoma clearance." (PMID 36439158, 2022).
Hepatic steatosis (2 papers, 2023 to 2025). Steatosis is a term used to denote lipid accumulation within hepatocytes. "The hypertrophy of chronic inflammation and white adipocytes in white adipose tissues was blocked and HFD-induced liver steatosis was suppressed by Il-27 gene transfer." (PMID 37600722, 2023). "IL-27 was also shown to attenuate ER stress and fatty acid uptake and to stimulate fatty acid oxidation via adenosine monophosphate-activated protein kinase (AMPK)/ autophagy signaling in cultured hepatocytes, thereby mitigating hepatic steatosis." (PMID 40794228, 2025).
hepatitis C (2 papers, 2010 to 2017). "IL-27 may thus be a suitable candidate for studies on combination therapies against hepatitis C, especially in light of the fact that novel IFN-based products are currently being developed." (PMID 20719000, 2010).
Hydrocephalus (2 papers, 2024 to 2025). Hydrocephalus is an active distension of the ventricular system of the brain resulting from inadequate passage of CSF from its point of production within the cerebral ventricles to its point of absorption into the systemic circulation. "We also found that the Eubacterium ruminantium group (genus) potentially increases the risk of normal-pressure hydrocephalus by decreasing the levels of IL-27." (PMID 39076985, 2024). "Next, we selected GMs causally associated with normal-pressure hydrocephalus and obstructive hydrocephalus, given that IL-17A and IL-27 are known to be associated with these conditions." (PMID 39076985, 2024). "Rigorous MR analysis revealed that IL-17A reduces the risk of obstructive hydrocephalus, while IL-27 reduces the risk of normal-pressure hydrocephalus." (PMID 39076985, 2024). "A range of inflammatory protective effects explains the reduced risk of normal-pressure hydrocephalus associated with IL-27." (PMID 39076985, 2024). "In Mendelian randomization analysis, Firmicutes phylum decreased the risk of obstructive hydrocephalus and Eubacterium ruminantium group (genus) increased the risk of normal-pressure hydrocephalus, potentially through increased IL-17 A and decreased IL-27 levels, respectively." (PMID 40859402, 2025). "Furthermore, we found that IL-17A and IL-27 reduced the risk of obstructive hydrocephalus and normal-pressure hydrocephalus, respectively." (PMID 39076985, 2024). "Furthermore, Firmicutes (phylum) reduced the risk of obstructive hydrocephalus by increasing the concentrations of IL-17A, whereas the Eubacterium ruminantium group (genus) potentially increased the risk of normal-pressure hydrocephalus by decreasing the concentrations of IL-27." (PMID 39076985, 2024). "Specifically, the Firmicutes (phylum) could reduce the risk of obstructive hydrocephalus by increasing the levels of IL-17A, while the Eubacterium ruminantium group (genus) potentially increased the risk of normal-pressure hydrocephalus by decreasing the levels of IL-27." (PMID 39076985, 2024). "In addition, Firmicutes (phylum) decreased the risk of obstructive hydrocephalus by increasing levels of IL-17A (mediating effect = 21.01%), while Eubacterium ruminantium group (genus) increased the risk of normal-pressure hydrocephalus by decreasing levels of IL-27 (mediating effect = 7.48%)." (PMID 39076985, 2024). "After removing confounders, univariable and multivariable MR analyses were performed using summary statistics to assess the causal relationships between GM, inflammatory factors (IL-17A and IL-27), and types of hydrocephalus." (PMID 39076985, 2024). "To explore the pathophysiological mechanisms of inflammatory factors in hydrocephalus, we analyzed IL-17A and IL-27, key players in inflammatory activation and immunoprotection." (PMID 39076985, 2024). "We reveal the connection between GM, inflammatory factors (IL-17A and IL-27), and hydrocephalus, which lays the foundation for unraveling the mechanism between GM and hydrocephalus." (PMID 39076985, 2024). "Its inhibition of certain inflammatory factors may also inhibit IL-27, which further may lead to the dysregulation of inflammatory factors, thereby promoting the development of normal-pressure hydrocephalus." (PMID 39076985, 2024). "Consequently, IL-27 could not mediate the causal association between Melainabacteria (class) and hydrocephalus." (PMID 39076985, 2024).
Hyperglycemia (2 papers, 2015 to 2023). An increased concentration of glucose in the blood. "However, it was recently reported that IL-27 can inhibit streptozotocin-induced hyperglycemia and pancreatic islet inflammation in an animal model and therefore could represents a potential novel therapeutic approach for T1D." (PMID 26636339, 2015).
hypothyroidism (2 papers, 2023 to 2024). Abnormally low levels of thyroid hormone. "Serum IL-27 levels demonstrated a compensatory increase in patients with subclinical hypothyroidism or hypothyroidism and showed an independent association with NAFLD." (PMID 37600722, 2023). "Correlation analysis was used to investigate the association between serum IL-27 levels and metabolic parameters in patients with hypothyroidism." (PMID 37600722, 2023). "Furthermore, the diagnostic accuracy of IL-27 was measured in the detection of NAFLD in hypothyroidism." (PMID 37600722, 2023). "Serum IL-27 levels are elevated in subjects with hypothyroidism and inversely correlate with the incidence of nonalcoholic fatty liver disease." (PMID 38872961, 2024). "In this study, a compensatory increase in the concentration of serum IL-27 was observed in patients with hypothyroidism or subclinical hypothyroidism." (PMID 37600722, 2023). "The purpose of this study was to assess the serum levels of IL-27 in patients with hypothyroidism and its relationship with NAFLD." (PMID 37600722, 2023). "Serum IL-27 levels were negatively associated with FBG, HOMAIR, subcutaneous fat, visceral fat, and TG, and positively associated with HDL-C in patients with hypothyroidism." (PMID 37600722, 2023). "Serum IL27 levels were significantly higher in subclinical hypothyroidism and hypothyroidism groups than in the euthyroidism group." (PMID 37600722, 2023). "Consistent with their findings, a compensatory increase in the concentration of serum IL-27 was observed in patients with hypothyroidism or subclinical hypothyroidism." (PMID 37600722, 2023). "In summary, serum IL-27 levels had a compensatory increase in patients with hypothyroidism or subclinical hypothyroidism and had an independent association with NAFLD." (PMID 37600722, 2023). "Correlation analysis between serum IL27 concentration and non-alcoholic fatty liver disease in hypothyroidism." (PMID 37600722, 2023). "More notably, lower circulating IL-27 levels in patients with hypothyroidism were independently related to NAFLD." (PMID 37600722, 2023). "The role of circulating IL-27 in improving NAFLD in hypothyroidism needs further investigation." (PMID 37600722, 2023). "This study manifests that altering circulating IL-27 levels could predict the occurrence of NAFLD in hypothyroidism." (PMID 37600722, 2023). "Hence, the purpose of this study was to assess the serum levels of IL-27 in patients with hypothyroidism and its relationship with NAFLD." (PMID 37600722, 2023). "IL-27 may combat hypothermia in patients with hypothyroidism through its febrile effects." (PMID 37600722, 2023). "Circulating IL-27 levels could predict the occurrence of NAFLD in hypothyroidism." (PMID 37600722, 2023). "Besides, NAFLD patients with hypothyroidism had lower IL-27 compared to those without NAFLD." (PMID 37600722, 2023).
Immunodeficiency (2 papers, 2017 to 2019). Failure of the immune system to protect the body adequately from infection, due to the absence or insufficiency of some component process or substance. "Here, we identify a patient with a causative homozygous mutation in IL6ST, encoding the human cytokine receptor subunit GP130, presenting with immunodeficiency and skeletal abnormalities including craniosynostosis, and demonstrate associated defects in IL-6, IL-11, IL-27, and OSM signaling." (PMID 28747427, 2017).
inflammatory skin disease (2 papers, 2012 to 2024). Inflammatory skin disorders covers a broad category that includes many conditions ranging in severity, from mild itching to grave medical health complications These disorders are common in people of all ages and races. "This study is the first to propose and validate IL-27 as the common and specific key molecule linking these two pruritic inflammatory skin diseases." (PMID 39735535, 2024).
lung adenocarcinoma (2 papers, 2013 to 2015). A carcinoma that arises from the lung and is characterized by the presence of malignant glandular epithelial cells. "The human lung adenocarcinoma cell line, A549, was treated with IL-27 at time points from 0.25 to 72 hours and analyzed for activated or tyrosine phosphorylated STAT1 (P-STAT1) and STAT3 (P-STAT3) proteins by Western blot." (PMID 24274066, 2013).
lymph node metastases (2 papers, 2020 to 2021). "High serum IL-27 level is associated with cancer presence and lymph node metastases in gastroesophageal cancer." (PMID 34604026, 2021). "However, another study found that IL-27 gene polymorphism was not a risk factor of tumorigenesis but a risk factor lymph node metastasis in PTC." (PMID 32655554, 2020).
lymphopenia (2 papers, 2018 to 2024). Reduction in the number of lymphocytes. "Episodes associated with lymphopenia showed lower levels of IL-27 (1.1 vs 1.4, p-value .002) but higher median PCT levels (0.3 vs. 0.2, p-value .03)." (PMID 30475852, 2018). "Episodes associated with neutropenia and lymphopenia have lower absolute concentrations of IL-27." (PMID 30475852, 2018). "This study aimed to explore the correlation between HIV-related CD4 lymphopenia and the inflammatory cytokines IL-23 and IL-27 in treatment-naive HIV patients." (PMID 39238692, 2024). "This prospective, observational study examined the correlation between HIV-related CD4 lymphopenia and inflammatory cytokines, namely IL-23 and IL-27." (PMID 39238692, 2024).
mesothelioma (2 papers, 2021 to 2022). A usually malignant and aggressive neoplasm of the mesothelium which is often associated with exposure to asbestos. "In addition to IL-27, IFN-γ levels also showed a similar correlation with sPD-L1 in pleural exudates, suggesting that both IL-27 and IFN-γ may contribute to PD-L1 expression in the mesothelioma microenvironment." (PMID 34439164, 2021).
myocarditis (2 papers, 2017 to 2022). Myocarditis is a condition that is characterized by inflammation of the heart muscle (myocardium). "Here, we showed that Ebi3, a subunit of IL-27, is not only important to ameliorate liver immunopathology, but more broadly it is also essential to suppress myocarditis caused by T. cruzi." (PMID 29033934, 2017). "Although IL-27 has been extensively characterized as a suppressive cytokine that prevents liver immunopathogenesis after T. cruzi infection, the mechanisms underlying its effects on T. cruzi-induced myocarditis remain largely unknown." (PMID 29033934, 2017). "Although IL-27 has been well characterized as a key inhibitor of liver inflammation caused by species of Trypanosoma, its role and implications to the outcome of T. cruzi-induced myocarditis is largely unknown." (PMID 29033934, 2017). "Therefore, the severity of the myocarditis is due to an accumulation of pathogenic IFN-γ-producing CD4 T cells rather than the higher production of IL-27." (PMID 29033934, 2017). "We believe that suppressive mediators, such as IL-27, are secreted in the later stage of the disease as an attempt of counterbalancing the pathogenic IFN-γ-producing CD4 T cells rather than being a causative factor directly associated with the severity of myocarditis." (PMID 29033934, 2017).
nasopharyngeal carcinoma (2 papers, 2014). A carcinoma arising from the nasopharyngeal epithelium. "Interestingly, a recent study has shown that gp130 is down-regulated in EBV-positive nasopharyngeal carcinoma primary tumors and determines the lack of activation of the Jak2/Stat pathway following IL-27 release, resulting in an impairment of NK cell function and immune surveillance." (PMID 24731550, 2014).
osteoarthritis (2 papers, 2008 to 2024). A noninflammatory degenerative joint disease occurring chiefly in older persons, characterized by degeneration of the articular cartilage, hypertrophy of bone at the margins and changes in the synovial membrane. "Similarly, IL-27 was elevated in RA synovial fluid than in osteoarthritis (OA) synovial fluid, and there were more CD14+IL-27+ cells in RA synovium but rarely in patients with OA." (PMID 38566992, 2024).
pemphigus (2 papers, 2016 to 2020). Pemphigus is a group of rare autoimmune diseases that cause blistering of the skin and mucous membranes (mouth, nose, throat, eyes, and genitals).This conditioncan occur at any age, but often strikes people in middle or older age. "Previous studies revealed that the blood concentration of IL-27 increased in pemphigus and psoriatic patients." (PMID 32616337, 2020). "The very strong correlation of IL-27 with the anti-Dsg3 IgG titers implicates a disease-specific function of IL-27 in the production of auto-ab in pemphigus." (PMID 26872212, 2016). "Here we show that IL-27 plasma concentrations are increased in pemphigus and in MG, an unrelated auto-ab mediated neurological autoimmune disease." (PMID 26872212, 2016). "Here, for the first time we can show that in pemphigus significantly elevated IL-27 plasma concentrations strongly correlate with Dsg-specific IgG auto-ab titers." (PMID 26872212, 2016). "Our data demonstrated increasing plasma concentrations of APC-derived pro-inflammatory cytokines, especially IL-27, in active pemphigus and MG." (PMID 26872212, 2016). "The further characterization of IL-21-producing T cells and of the role of IL-27 will lead to a more defined understanding of the auto-ab response in pemphigus." (PMID 26872212, 2016). "In our study we noticed a strong correlation of IL-27 plasma concentrations with TNF-α in pemphigus patients which might support an additional pro-inflammatory function of IL-27 in pemphigus as well." (PMID 26872212, 2016). "Furthermore, the plasma concentrations of TNF-α were also increased in active pemphigus and correlated very strongly with the plasma concentrations of IL-27 (rs = 0.87) supporting a pro-inflammatory function of IL-27 in pemphigus." (PMID 26872212, 2016). "Following the strong correlation of the IL-27 concentrations with anti-Dsg3 IgG titers, we next addressed the question how the auto-ab production in pemphigus could be mediated by IL-27." (PMID 26872212, 2016). "However, IL-27 plasma concentrations strongly correlated with the IgG auto-ab titers only in pemphigus suggesting a disease-specific function of IL-27 in the pathogenesis of pemphigus." (PMID 26872212, 2016). "Strikingly, IL-27 was significantly elevated in active pemphigus and MG." (PMID 26872212, 2016). "Thus, antagonizing IL-27 and IL-21-production may represent a novel therapeutic option in pemphigus." (PMID 26872212, 2016). "In pemphigus and MG, the plasma concentrations of the APC-derived immunomodulatory cytokine IL-27 were highly increased." (PMID 26872212, 2016). "We investigated the plasma concentrations of the APC-derived immunomodulatory cytokine IL-27 and the pro-inflammatory cytokines IL-6 and TNF-α in active and remitting pemphigus patients, MG patients and HC." (PMID 26872212, 2016). "The aim of this study was to investigate APC-derived cytokines, including IL-27, and their relation to CD4+ T cell subsets and to the auto-ab response in pemphigus." (PMID 26872212, 2016). "As the therapy with prednisolone significantly impacted APC numbers in a dose-dependent manner pemphigus patients with a prednisolone therapy of >10mg/d were not included in the analysis of the APC-derived IL-27 and Dsg-specific IgG." (PMID 26872212, 2016). "Interestingly, in the remitting pemphigus patients (n = 3) neither IL-27 nor IL-6 or TNF-α could be detected in distinct amounts." (PMID 26872212, 2016). "However, the function of IL-27 in the pathogenesis of pemphigus has not yet been characterized." (PMID 26872212, 2016).
posterior uveitis (2 papers, 2012). Inflammation of the choroid as well as the retina and vitreous body. "In this study, we investigated the association of three immune-related SNPs in the CFH, KIAA1109, and IL27 genes with non-infectious intermediate and posterior uveitis." (PMID 22876110, 2012). "Taking together, we hypothesize that CFH-rs800292, IL-27-rs4788084, and rs4505848 within the KIAA1109/Testis nuclear RNA-binding protein (Tenr)/IL2/IL21 gene cluster might be involved in the pathogenesis of IU and posterior uveitis." (PMID 22876110, 2012).